RNU7-148P (RNA, U7 small nuclear 148 pseudogene)
Gene: Small nuclear RNA gene on chromosome 2 (167,631,480 to 167,631,541, reverse strand). Ensembl gene ENSG00000238357.
Homologues: Orthologues: macaque U7 (90% identical). Paralogues in human: RNU7-110P (85% identical), RNU7-35P (84% identical), RNU7-88P (84% identical), RNU7-113P (82% identical), RNU7-187P (82% identical), RNU7-97P (82% identical), RNU7-152P (81% identical), RNU7-67P (81% identical), RNU7-70P (81% identical), RNU7-82P (81% identical), RNU7-111P (79% identical), RNU7-128P (79% identical), and 140 more.